IL6 (interleukin 6)
Diseases named in the same sentence as IL6 in open-access papers (continued):
Sharing a sentence is not in itself a finding about the gene and the disease.
cancer (continued). "Based on these facts, it is plausible that patients with a surge in IL-6 after surgery are at high risk of cancer metastasis, and these patients can exhibit poor outcomes." (PMID 37194025, 2023). "Interleukin-6 (IL-6) and interleukin-8 (IL-8) play key roles in inflammation and have been implicated in cancer progression." (PMID 38187701, 2023). "Elevated expression of IL-6 was associated with histopathological grade and metastases in malignant tumors." (PMID 36693957, 2023). "In the metastatic microenvironment, cancer cells acquire stem-like properties through paracrine interactions between cancer-associated fibroblasts (CAF) and cancer cells, which include IL-6." (PMID 37190171, 2023). "Recently, interleukin (IL)-6, an inflammation-associated cytokine with multifaceted effects, has emerged as a critical therapeutic target in cancer treatments." (PMID 37696858, 2023). "The high expression of IL-6 is associated with poor prognosis and can be used as a diagnostic marker of inflammation and malignant tumor." (PMID 36845384, 2023). "Since its role in mediating autophagy is associated with cancer cell survival, this also reflects IL-6’s role in linking inflammation and autophagy." (PMID 37893079, 2023). "IL-6 has been implicated in the dissemination of cancer cells leading to metastasis since it drives cancer cell proliferation and invasiveness while suppressing apoptosis." (PMID 37397366, 2023). "For example, binding of galectin-3 to TF on cancer-associated transmembrane mucin protein MUC1 increases cancer cell heterotypic adhesion to vascular endothelium and promotes endothelial secretion of metastasis-promoting cytokines such as GM-CSF and IL-6." (PMID 37612278, 2023). "Altogether, these results imply that Panx1 contributes to genotoxic-induced IL-6 and is linked to poor clinical outcomes in cancer patients." (PMID 37696858, 2023). "Inflammatory mediators, including tumor necrosis factor-alpha (TNF-α), interleukin-6 (IL-6), and interleukin-10 (IL-10), have been implicated in cancer metastasis." (PMID 38116560, 2023). "Aberrantly produced cytokines, in particular IL-6, are associated with cancer metastasis, therapeutic resistance, and poor survival outcomes in cancer patients [,30,72]." (PMID 37385076, 2023). "Through experiments, they proved that objective associated systematic interleukin-6 indirectly enhances preamble atom expression via increased breakthrough cancer cell E2 production." (PMID 36836694, 2023). "Evaluation of small-molecule agents that inhibit IL-6 and its associated signaling pathway has been undertaken, exploring a potential approach in cancer treatment." (PMID 37892997, 2023). "The top Cancer Hallmark pathways enriched in the SI rats, compared with the group-housed rats, included IFNα, IFNγ, and inflammatory responses, and IL6/JAK/STAT3 and TNFα signaling via NFκB." (PMID 36980301, 2023). "Our study shows that common pro-inflammatory and SASP-associated factors, TNFα and IL-6, were both significantly reduced by sirolimus treatment in both normal and early cancer, which confirms a role of mTOR signaling in promoting the secretion of SASP factors." (PMID 37904250, 2023). "IL-6/IL-8-JAK2 signaling activated by cancer-associated fibroblasts (CAFs) conferred resistance to a bromodomain and extra-terminal (BET) inhibitor in colorectal cancer cells." (PMID 36834846, 2023). "VEGF-A, TNF-α, CCL2, and IL-6 were positively associated with muscle-associated enzymes among the Cancer TIF1-γ-DM patients." (PMID 36357631, 2023). "Inflammatory cytokines (e.g., IL-6) show promising results as potential prognostic markers to predict the risk of cancer recurrence and patient death." (PMID 37440925, 2023). "Our previous study found that cancer-secreted IL-6 can upregulate the expression of KDM2A to promote further the transition of cells into cancer-associated fibroblasts (CAFs)." (PMID 37821959, 2023).
cancer (continued). "Inflammatory factors can modulate the response of cancerous cells to chemotherapy, and anti-cancer drugs can cause the expression of some of the cytokine genes, including those of TNFα, IL-1β, and IL-6." (PMID 36834426, 2023). "Elevated IL-6 or IL-8 secretion is associated with proliferation, angiogenesis, and survival of many cancer cell lines." (PMID 37402454, 2023). "We are aware of some literature reporting IL-6 as an independent risk factor for prognosis in cancer patients." (PMID 37124547, 2023). "A wide variety of cytokines, many of which have been implicated in cancer pathogenesis, are known to signal through receptors that include gp130, such as IL-6, IL-11, LIF, and OSM." (PMID 38022653, 2023). "In recent years, the relationship between IL-10 and IL-6 gene polymorphisms and cancer have attracted great attention." (PMID 37077342, 2023). "IL-6 is an inflammatory cytokine that is closely related to inflammatory reactions and is a cancer-associated inflammatory factor." (PMID 37817809, 2023). "IL-6 or IL-6R genetic polymorphisms have been reported to be associated with risk or prognosis in patients with some cancers." (PMID 38469154, 2023). "Several inflammatory mediators, such as tumor necrosis factor-alpha, interleukin (IL)-6, and IL-10, have been linked to cancer initiation and progression." (PMID 36836114, 2023). "IL-6 is a multifunctional cytokine that has long been linked with malignant transformation, cancer cell proliferation and progression of HGSOC." (PMID 36765633, 2023). "Cytokines such as tumor necrosis factor-alpha (TNF-α), interleukin-6 (IL-6), and IL-10 have been linked to cancer spread." (PMID 36771154, 2023). "The source of these factors was established with scRNA-seq and it was concluded that docetaxel-induced cancer cell proliferation is associated with IL-6 and C-GSF secretion from inflamed stromal cells." (PMID 37703292, 2023). "It has been reported that IL-6 or IL-6R genetic polymorphisms are associated with risk or prognosis in patients with some cancers." (PMID 38469154, 2023). "Naïve activated fibroblasts communicate with epithelial cells via inflammatory cytokines such as IL-6, TGFβ and fibroblast growth factor, like cancer-associated fibroblasts with cancer cells." (PMID 37439962, 2023). "The consideration of IL-6 levels detected in the serum of various type of cancer patients as potential diagnostic and predictive biomarker has been discussed in the literature." (PMID 37173331, 2023). "Unadjusted higher levels of CRP, IL-6, and IL-8 were associated with greater frailty in the non-cancer control group." (PMID 37213604, 2023). "Data from observational studies also revealed that increased levels of IL-6 were associated with both coronary heart disease and cancer." (PMID 36830690, 2023). "Related to oral hygiene as a risk factor for carcinogenesis, Candida and polymicrobial oral biofilms have been reported to increase the expression of the cancer-associated inflammatory cytokines IL-6 and IL-8 in normal and cancer cells." (PMID 37504236, 2023). "In one study, the conversion of normal fibroblasts to cancer-associated fibroblasts (CAFs) under co-culture conditions with OSCC lines was associated with the regulation of IL6 and CXCL1, with the latter acting in a cancer-specific manner." (PMID 37046588, 2023). "High levels of C-reactive protein (CRP), interleukin 6 (IL- 6), and interleukin 10 (IL-10) are associated with poor performance, weight loss, and worse prognosis in cancer patients." (PMID 38067294, 2023). "IL-6 acts directly on cancer cells to induce the expression of STAT3-encoding proteins driving cancer proliferation, i.e., cyclin D1 and survival, i.e., BCL2-like protein 1 (BCL-xL)." (PMID 37480115, 2023). "It has been reported that IL-6 (−634G>C) and IL-6R (48892A>C) genetic polymorphisms are associated with the risk or prognosis in patients with some cancers." (PMID 38469154, 2023).
cancer (continued). "A study of cancer patients showed that fatigue severity was significantly associated with IL-6 levels." (PMID 37215213, 2023). "Cancer cells release pro-inflammatory factors such as IL-6, IL-1a, TGF-β, and TNF-ɑ to activate cancer-associated fibroblasts (CAF) into iCAF, and radiation induces tumor cells to secrete large amounts of cytokines with radioresistance." (PMID 37322433, 2023). "High levels IL-4, IL-10, and IL-6 expression have been linked to the development of several cancer types, improved EMT, and the development of treatment resistance via the triggering of anti-apoptotic pathways and metastasis." (PMID 37941832, 2023). "A similar combined action of sOPN and iOPN is associated with head and neck (HNC) cancer progression induced by cancer-associated fibroblast-derived IL-6." (PMID 36769264, 2023). "Cancer-associated fibroblasts (CAFs) expressed significant levels of the IL-6 cytokine, while RT4 bladder cancer cells contained the IL-6R receptor." (PMID 36140470, 2022). "Inflammation and cancer are closely related, and IL6 is associated with nearly all of the hallmarks of cancer." (PMID 35682546, 2022). "Third, physical activity is associated with lower levels of systemic inflammation by altering inflammatory cytokines or adipokines (e.g., C-reactive protein, adiponectin and interleukin-6), which are associated with a higher risk of cancer." (PMID 36510257, 2022). "There is accumulating evidence of IL-6 secreted by the cancer-associated fibroblasts that plays an important role in chemoresistance." (PMID 36560531, 2022). "IL-6 not only amplifies cancer-causing chronic inflammation but also mediates the internal mechanism of tumour cells that drive cancer progression." (PMID 36159866, 2022). "Pyrimidine, cholesterol, IL-6, and exosomal miRNA released by TAMs are also associated with enhanced therapy resistance in various cancer cells." (PMID 35799889, 2022). "In adjusted mixed linear models, weight loss is strongly related to the levels of cancer-associated biologically active substances, including reduced interleukin-6 (IL-6) levels and increased adiponectin levels." (PMID 36578551, 2022). "Inflammatory cytokines including TNF-α, IL-6 and IL-8 play a major role in cancer-associated immune response." (PMID 36354990, 2022). "TNF-α and IL-6 are two key inflammatory cytokines linked to chronic inflammatory diseases and cancer." (PMID 36010601, 2022). "Accordingly, the presence of intratumoral IL-17A+ IL-23R+ IL-6+ CD4+ T cells was described to be associated with the development of colitis-associated cancer." (PMID 36428508, 2022). "Although various humoral factors are known to be involved in cancer progression, IL-6 has recently been associated with various carcinomas including HNSCC." (PMID 35089951, 2022). "Among the cytokines linked to inflammation-associated cancer, IL-6 drives many cancer hallmarks through the downstream activation of the STAT3 (Signal transducer and activator of transcription 3) signaling pathway." (PMID 36547079, 2022). "IL-6/JAK/STAT3 signaling pathway is abnormally hyperactivated in various cancers, and is associated with poor prognosis." (PMID 35090515, 2022). "It has been shown that IL-6 mediates malignant changes while being the primary driver behind anti-apoptotic mechanisms, and serves as an essential biomarker in determining cancer risk, prognosis, and diagnosis." (PMID 35711466, 2022). "Cancer induces inflammatory cytokines, such as interleukin (IL)-6 and tumor necrosis factor (TNF)-α, and causes LBW." (PMID 36294421, 2022). "In cancer cachectic mice, IL-6 causes a decrease in fat content and stimulates adipose tissue browning." (PMID 36499637, 2022). "Previous studies have demonstrated that Inflammatory cytokines such as IL-17A and IL-6 were closely linked with cancer associated inflammation." (PMID 35436305, 2022).
cancer (continued). "Hepatic alterations have been associated with cancer-induced muscle wasting and furthermore liver fibrosis-induced muscle atrophy was promoted by elevated levels of circulating IL-6, TNF-α and myostatin during progression of liver disease." (PMID 35994202, 2022). "This specific cytokine pattern appears to have a prognostic effect, as high interleukin 6 or interleukin 10 serum concentrations are associated with poor prognosis in independent cancer types." (PMID 36579330, 2022). "On the other hand, the activation switches for cancer, such as the transcriptional activation and cell proliferation caused by IL-6 signaling, IL-1 signaling, and JAK/STAT signaling, were activated at 6 h after treatment with TPA." (PMID 35328637, 2022). "We observed that the AP3S1 overexpression was positively associated with many malignant pathways in pan-cancer, such as IL6 JAK STAT3 signaling, IL2 STAT5 signaling, TGF BETA signaling, interferon gamma response, and interferon alpha response." (PMID 35874816, 2022). "IL-6 can directly cause cancer cell proliferation, can also promote the production of other inflammatory factors in TME, and recruit large numbers of immune cells." (PMID 36291659, 2022). "This aberrant activation of downstream IL-6 signalling pathways is associated clinically and experimental with poor outcomes in oncological patients or cancer models." (PMID 36429126, 2022). "During this process, the signal transducer and activator of transcription 3 (STAT3) was not only a downstream target of interleukin-6 (IL-6) but also a part of the positive feedback loop that underlays the epigenetic switch between inflammation and cancer." (PMID 35434143, 2022). "Many patients with cancer cachexia suffer from inflammation associated with elevated cytokines, such as interleukin-1beta (IL-1β), interleukin-6 (IL-6), and tumor necrosis factor (TNF)." (PMID 36358681, 2022). "Our study demonstrated that RasGRP1 is a key regulator that promotes production of the proinflammtory cytokine IL-6 and decreases the probability of inflammation-associated cancer developing during acute inflammation." (PMID 36385095, 2022). "In contrast to TNFα, circulating levels of IL-6 were shown to correlate with weight loss in cancer patients and with reduced survival." (PMID 36078078, 2022). "Aberrant expression of IL-6 occurs in multiple cancer types and is associated with poor clinical prognosis and metastasis." (PMID 35371975, 2022). "The incidence of cancer and cancer-related death was also associated with a high level of circulating IL-6, TNFα, and CRP in a five-year follow-up of elderly individuals." (PMID 36369012, 2022). "The principal cause of FID in cancer is the release of pro-inflammatory cytokines such as IL-6, IL-1, TNF-α, and IFN-γ, which amplify hepcidin synthesis and thereby reduce the quantity of iron released into the circulation." (PMID 36143875, 2022). "The anaphylatoxins produced by the complement system have proven to play a pivotal role in inflammation and cancer progression, and its downstream effectors, like Interleukin 6, cause the constitutive activation of STAT3." (PMID 35800364, 2022). "High levels of IL-6 in the blood of cancer patients are associated with worse prognosis and survival." (PMID 35053570, 2022). "In hospitalized cancer patients with high grade DAEs, elevated elafin, IL-6, and TNF-α were shown to be associated with higher all-cause mortality." (PMID 35770005, 2022). "In cancer cachexia, the pro-inflammatory mediator IL-6 is associated with the dysregulation of skeletal muscle mitochondria." (PMID 36499157, 2022). "While IL-6 is associated with many liver pathologies and cancers, IL-6 also plays an important role in liver regeneration." (PMID 36389782, 2022). "Muscle atrophy, cancer, and the development of liver acute phase proteins have all been linked to IL-6." (PMID 35159388, 2022).
cancer (continued). "Inhibition of MALT1 protease activity did not affect PCa cell survival nor activation of NF-κB and JNK signalling, but reduced expression of cancer-associated genes, including the cytokine IL-6." (PMID 36009554, 2022). "Sometime later, in 2018, a systematic review of the epidemiological evidence revealed an association of higher concentrations of circulating IL-6 in cancer patients than healthy controls." (PMID 36742002, 2022). "CAFs, on the other hand, are the principal cause of multipurpose interleukins (IL-6, IL-8) that modulate cancer stem cell–differentiated cancer cell balance and tumor microenvironment neo-angiogenesis." (PMID 35740570, 2022). "Several studies have demonstrated that the monoclonal antibody-mediated neutralisation of IL-1 or IL-6 ameliorates cancer cachexia characterised by loss of skeletal muscle mass and WAT browning." (PMID 35406121, 2022). "Hypogonadism at baseline, found in approximately one of four cancer survivors, was associated with higher IL-6 levels." (PMID 35135482, 2022). "TRP score was positively associated with malignant pathways in pan-cancer, such as IL6–JAK–STAT3 signalling, interferon-gamma response, and inflammatory response." (PMID 35493463, 2022). "Some reports have shown that procalcitonin and IL-6 are associated with the liver metastasis of cancer." (PMID 35203589, 2022). "Raised levels of IL-6 have been associated with cancer cell proliferation, angiogenesis and metastasis." (PMID 34951691, 2022). "Increased IL-6 production by neoplastic cells has been implicated in pro-oncogenic gene mutations in cancer cells that enhance IL-6 gene expression and secretion." (PMID 35406728, 2022). "Intriguingly, upregulated lncRNA MALAT1 in GC cells protects IL-6 from autophagic degradation and thus aggravates IL-6-activated cancer-associated fibroblast conversion." (PMID 36353541, 2022). "Previous studies focused on adults have found some associations between interleukin-6 (IL-6), interleukin-8 (Il-8), tumor necrosis factor α (TNFα) SNPs, and clinical outcomes in cancer patients." (PMID 35335997, 2022). "We observed that the TRP score was positively associated with many malignant pathways in pan-cancer, such as IL6–JAK–STAT3 signalling, interferon-gamma response, and inflammatory response." (PMID 35493463, 2022). "IL-6 is a pro-inflammatory cytokine that participates in chronic inflammatory conditions, which is one of the leading causes of cancer progression." (PMID 35927755, 2022). "In general, high levels of IL-6 cytokine are associated with increased inflammatory reaction, which in turn is closely related to the occurrence and development of cancer." (PMID 35707470, 2022). "Consistent with these preclinical findings, analysis of RCC patient datasets from TCGA revealed a positive association between IL-6 levels and immunosuppressive cells, such as Tregs, MDSCs, and cancer-associated fibroblasts." (PMID 36497467, 2022). "More importantly, resveratrol has been shown to stop cancer-associated fibroblasts from secreting IL-6." (PMID 35566016, 2022). "To begin understanding cytokine-induced adipocyte lipolysis, we initially compared adipocyte lipolysis by the cancer cachexia-associated cytokines IL-6 and LIF to that of the well-characterized lipolytic factor and β-adrenergic agonist isoproterenol." (PMID 35785158, 2022). "Accordingly, factors (IGFBP5, CLCF1 and IL6) reported to be secreted by cancer-associated fibroblasts (CAFs) showed higher expression level in the high-risk group." (PMID 35711936, 2022). "The cytokine ratio, IL-10/IL-6 has been previously reported as a marker of immunosuppression associated with malignant tumors and/or with intense physical exercise." (PMID 35327367, 2022). "Intriguingly, IL-6 levels were positively correlated with immunosuppressive cells such as Tregs, MDSCs, and cancer-associated fibroblasts." (PMID 36497467, 2022).